MMP9 (matrix metallopeptidase 9)
Diseases named in the same sentence as MMP9 in open-access papers (continued):
Sharing a sentence is not in itself a finding about the gene and the disease.
tumor (continued). "MMP9 expression is not specific of a single-cell population, being secreted in the ECM by both tumor and healthy cells." (PMID 36048342, 2022). "Unlike what has been observed for LCN2 and MMP9, the SLC22A17 expression was downregulated in most tumor types (66.7%) compared to normal tissue samples." (PMID 36211450, 2022). "More normal and tumor saliva samples should be collected and set the positive or negative cut-off value of HGF and MMP9." (PMID 35545767, 2022). "Besides, the conjugate showed a high antitumor effect in SGC-7901 tumor model with a tumor inhibition rate of 59.57%, and which might be mediated by increasing the levles of TNF-α, Bax and Caspase-3 and reducing the levels of CD34, VEGF, MMP-2, MMP-9 and Bcl-2." (PMID 36463199, 2022). "The addition of MMP-9 to GLV-1H68 did not change virus infectivity in vitro but improved tumor regression and virus titers in tumors in the PC-3 xenograft tumor model of prostate cancer." (PMID 35155581, 2022). "In terms of the tumor inhibition rates, histopathology, and inhibition of MMP2 and MMP9, it was observed that although the Hespintor was not as effective as Sorafenib, two factors should be considered." (PMID 33391431, 2021). "In tumor tissue, we found that the expression of MMP-2 was not statistically significant between the two groups, while the expression of MMP-9 in the LF group was higher than that in the control group." (PMID 34819565, 2021). "We demonstrated that the enzymatic product of ALDH1A2, retinoic acid (RA), modulated the expression and activity of MMP-2 and MMP-9 in macrophages, but not in GBM tumor cells." (PMID 34572134, 2021). "In vitro study of GPNMB-expressing tumor cells showed no impact on cellular growth or death but increased expression of MMP-3 and MMP-9 as well as increased invasiveness." (PMID 34108545, 2021). "Collectively, the pathway analysis of MMP2/MMP9 co-expressed genes showed their involvement in EMT and Immune system pathways, emphasizing their importance in tumor progression, although the mRNA expression levels were not directly correlated with prognosis." (PMID 34830271, 2021). "All neoplasms expressed MMP-2, MMP-9, MMP-14 and TIMP-1 independent of the infection state but displayed a variable distribution and intensity as demonstrated by immunohistochemistry." (PMID 33808256, 2021). "Only VEGF was more expressed by CD49a+Eomes+ cells in nontumorous liver tissue, while in the tumor, CD49a+Eomes+ cells expressed higher levels of VEGF, PlGF, IL-8, MMP-9, angiogenin, and CXCL10 (IP-10)." (PMID 33802077, 2021). "Moreover, our observations that reductions in MMP-9 at T1and T2 were greater when patients received combined paravertebral anesthesia with general anesthesia seem consistent with the hypothesis that PVB has little effect on immune function, thus strengthens immune defenses against tumor progression." (PMID 32143570, 2020). "GB is a highly invasive tumor, interestingly we found that hypoxia did not induce MMP-2, MMP-9, PLAU, uPAR, CTSA, or ANXA2 gene transcription in our GB cell models." (PMID 32867190, 2020). "We aimed to measure ELN gene expression and its related MMP9, MMP12 and TIMP3 gene levels in tumor from CRC patients compared to adjacent non-tumor tissues and healthy controls in existing array datasets." (PMID 32171282, 2020). "Levels of this protein (CD44 isoform 2) also increased in the treatment with tumor cfDNA in PNT-2, however, MMP9 protein levels have not been changed." (PMID 33303880, 2020). "In non-neural cell types, such as tumor cells, COX-2-derived PGE2 increases MMP-9 expression and activity." (PMID 32973660, 2020). "This leads to the adhesion of non-classical monocytes to vessel walls near the tumor, followed by the production of IL-6, MCP-1/CCL2 and MMP-9 by monocytes." (PMID 32466280, 2020). "The level of Matrix metallopeptidase 9 (MMP-9), which is produced by MDSCs and promotes tumor progression, was diminished in mice lacking the IL-17 receptor." (PMID 32121394, 2020).
tumor (continued). "Although not used diagnostically, the role of MMP-9 has been well described in CRC invasion and metastasis, enabling tumor growth and cancer cells to escape into circulation." (PMID 31889941, 2019). "Transgenic mice lacking MMP-9 reduced the tumor invasiveness in a mouse model of SCC whereas, transplanting MMP-9 producing bone marrow cells increased tumor invasiveness." (PMID 31134198, 2019). "This led to the selection of seven antigens found to be overexpressed in both mouse MM tumor lines under investigation and that were nearly absent in all other mouse normal tissues: KIF20A, KIF2C, MMP9, MNDA, OLFML2B, TROAP, and ULBP1." (PMID 31428586, 2019). "We found that TFF1 exhibited lower expression while MMP9 and CD34 showed higher expression in tumour tissues compared than in adjacent non-cancerous tissues." (PMID 30612555, 2019). "In examining the effect of SDS3 on the primary tumor, once tumor foci had been established within the TME, MMP9 no longer played a critical role in tumor growth, rendering SDS3 ineffective." (PMID 31727800, 2019). "The pro-tumor N2 phenotype is characterized by increased expression of angiogenesis and invasion promoting factors CXCR4, VEGF and MMP-9 with absent IFN-β and is acquired by neutrophils following the TGF-β treatment." (PMID 30927923, 2019). "In fact, EVs released by renal CSCs and not by differentiated tumor cells enhance the formation of lung metastases by the upregulation of MMP2, MMP9 and VEGF receptors by lung endothelial cells." (PMID 31013896, 2019). "In PyMT mice, SAHA delays tumor growth and reduces tumor burden and inhibits TAM infiltration of estrogen receptor-negative (ER-) mammary tumors while decreasing M-CSF and MMP-9 levels in these tumors." (PMID 29755698, 2018). "In a murine model of breast cancer, IL-12 treatment reduced the levels of MMP-9, but not MMP-2, and it also reduced tumour cell production of VEGF by up-regulation of IFN-γ production leading to the suppression of tumour angiogenesis." (PMID 29555826, 2018). "In the GC group, PGC was rarely expressed while the expression levels of tumor markers including MG7‐Ag, MMP9, and Ki‐67 were high, so there was also no coexpression relationship between them." (PMID 29963765, 2018). "In the NeuT tumor model, however, anti-PDL1 treatment alone neither exerted antitumor efficacy nor further potentiated the efficacy of anti–MMP-9 in combination." (PMID 30500835, 2018). "Here, several tumor EMT markers (Twist1, Snail, MMP1, and MMP9) were evaluated, but metformin did not inhibit EMT in MCF7/ADR." (PMID 29416762, 2018). "With the results above, KCTD11 was found to be regulating not a few molecules related to tumor progression, such as Cyclin D1, CTGF, MMP9 and Slug." (PMID 28465479, 2017). "We further determined the expression levels of MMP2 and MMP9 in our NSCLC cohort; the results revealed that the expression level of MMP9 but not MMP2 was correlated with MIAT to express highly in tumor tissue and advanced stage." (PMID 29228680, 2017). "Though OPN was not essential for tumor formation, it was indicated that OPN is involved in early stage intestinal tumorigenesis in part by upregulation of MMP-3, MMP-9, and MMP-13, and infiltration of macrophages and neutrophils." (PMID 28505114, 2017). "However, matrix metalloproteinases (MMPs) including MMP-2 and MMP-9 showed significant decrease after ApoA-1 treatment in both two cell lines, which indicating ApoA-1 might inhibit CTC formation via impairing extracellular matrix degradation properties of tumor cells." (PMID 27683106, 2016). "Thus, even though no data was available on corresponding serum levels, the lack of prognostic value observed for MMP2 and MMP9 tumor expression in this retrospective cohort may argue in favor of a predictive and specific impact of these markers for bevacizumab benefit." (PMID 26921265, 2016).
tumor (continued). "TGF-β reduces the effect of tumor-entrained neutrophils (TEN; a subset of CD11b+Ly-6GH+MMP-9+ cells not present in healthy individuals), which typically kill tumor cells by producing hydrogen peroxide." (PMID 28105409, 2016). "Our results showed that inhibition of MMP-9 prevented co-culture induced proliferation; however, addition of activated MMP-9 to tumor cells did not increase proliferation." (PMID 27888810, 2016). "We showed a role for FABP5 modulation of MMP9 secretion, and not MMP2, in TNBC cells, which plays an important role in degrading the extracellular matrix and the invasion of tumor cells." (PMID 25779666, 2015). "The MMP9 immunoreactivity was generally adjacent to human nuclear antigen (HNA)-positive cells, suggesting that it is being expressed by tumor cells, rather than by HNA-negative murine host stromal cells." (PMID 26452220, 2015). "Although most MMPs in cancer tissue are produced by stromal rather than cancer cells, clinical evidences showed the tumor cell-expressed MMP-2 and MMP-9 are related with HCC progress." (PMID 24996644, 2014). "Our preliminary data shows that the MMP-2, MMP-9, p-AKT, pERK, pMAPK, and JNK were increased significantly in transfected SAOS-2 tumor cells, while caspase-3 and Ki-67 did not change significantly (data not shown)." (PMID 25300797, 2014). "Although 10 mg/kg artesunate did not significantly inhibit A549 xenograft tumor proliferation (P > 0.05), artesunate decreased the ICAM-1 and MMP-9 protein levels in the mouse model (P < 0.05)." (PMID 24229621, 2013). "In this study, we demonstrate that ZF21 also regulates invasion of tumor cells, whereas it does not affect the overall production of MMP-2, MMP-9, and MT1-MMP by the cells." (PMID 23382803, 2013). "By using chicken chorionallantoic membrane (CAM), a study showed that the cooperation of u-PA and MMP-9 is essential for tumor metastasis; however, the absence of MMP-9 or u-PA led to impaired invasive abilities in the tumor cells." (PMID 24039823, 2013). "In a first step, the BM of an existing vessel is degraded by MMPs that are expressed by ECs, such as MMP-1, MMP-2, MMP-9, and MT1-MMP/MMP14, at which MMP-9 is required for tumor vasculogenesis rather than angiogenesis." (PMID 21941547, 2012). "Surprisingly, epithelial MMP-9 and stromal TIMP-2 expressions correlated with poor survival, while tumor type, grade and stage did not." (PMID 22200690, 2012). "We have observed by various means that MMP-9 is not significantly expressed by neither irradiated nor control lung CAFs, contributing to the notion that MMP-9 is primarily expressed by tumour-infiltrating inflammatory cells, rather than by CAFs." (PMID 22500976, 2012). "We also found that apigenin specifically inhibited MMP-9, but not MMP-2 expression in both tumor tissues and cancer cells." (PMID 22837693, 2012). "In contrast, tumour cells secreted abundant MMP-3 and MMP-9 following TNF treatment, suggesting the use of nonredundant pathways by IL-17 and TNF." (PMID 19014637, 2008). "There have been reports linking other extracellular proteases, such as MMP-9, MMP-1 and uPA with FAK signalling in other tumour cell types, but until now MMP-2 has not been reported to be involved." (PMID 18349846, 2008). "Plasma concentrations of MMP1, MMP3, MMP9, TIMP2, and the MTC1 did not correlate to tumour stage, grade, lymph node involvement, or distant metastasis." (PMID 16901349, 2006). "Plasma concentrations of MMP1, MMP3, MMP9, TIMP2, and MTC1 did not correlate to tumour stage and grade, but also to lymph node involvement or distant metastasis (data not indicated)." (PMID 16901349, 2006). "Immunohistochemical staining showed that no expression of PCNA, MMP-9, and CD44v6 was detected within the treated tumour cells in the HIFU group, indicating that the treated tumour cells lost the abilities of proliferation, invasion, and metastasis." (PMID 14676799, 2003).
tumor (continued). "MMP-9 and TIMP-1 mRNA were similarly observed in the peritumour stroma cells rather than in tumour cells themselves." (PMID 7669564, 1995). "Similarly, RTKN2 exacerbated the tumor development by regulating MM92 and MMP9 expression in non-small cell lung cancer." (PMID 38155217, 2023). "Similarly, a lack of correlation was confirmed for the patients who had tumor cells in the surrounding lymph nodes as compared to those whose lymph nodes were free (TIMP1, p = 0.6652; MMP2, p = 0.5166; MMP9, p = 0.9766; collectively, p = 0.8416)." (PMID 37509417, 2023). "On the other hand, the same investigation found that MMP-2 and MMP-9 levels remained constant across OSCC stages, arguing that they could not be used as suitable surrogate marker of tumor-invasiveness potential." (PMID 37445908, 2023). "Mechanistically, NET-derived NE and MMP-9 proteases were required for reactivating dormant cells through extracellular matrix (ECM) remodeling rather than through direct contact between NETs and dormant tumor cells." (PMID 36384979, 2022). "By comparing metastasis-related genes expressed in paired nontumor tissue– and tumor tissue–purified monocytes, we found that levels of MMP9, VEGFA, and CCL8 were all increased in the tumor monocytes compared with the nontumor monocytes, with CCL8 exhibiting the most marked upregulation." (PMID 35362480, 2022). "Upon validation, primary tumor tissues from the MFBD mice exhibited significant increases in TNFα expression compared to tumors from the OOBD fed mice as well as increased an expression of S1PR1 and MMP9; however, these were not statistically significant." (PMID 34371939, 2021). "Emodin treatment (40 mg/kg, i.p) did not alter the tumor size and weight, but suppressed macrophage infiltration in the tumors (particularly CD206+ M2-like macrophages), increased CD4+ and CD8+ T cells, and decreased the expression of Vimentin and MMP9." (PMID 34073059, 2021). "Moreover, PcrV treatment did not affect the expression levels of genes (e.g., Cox2, Mmp9, Vegfa, and Hif1a) or proteins (e.g., COX2 and vimentin) related to tumor growth and metastasis, or the metastatic ability of LLC cells." (PMID 34900687, 2021). "Thus at the doses of inhibiting tumor metastasis RGDV-gemcitabine, but not gemcitabine, effectively decrease of serum MMP-2 and MMP-9 of C57BL/6 mice." (PMID 32978501, 2020). "Although both MMP2 and MMP9 were present in primary tumors, SDS3 reduced the metastatic growth of VO-PyMT probing cells in the lungs of MMTV-PyMT mice without affecting primary tumor growth." (PMID 31727800, 2019). "Finally, the specificity of the PA-L1 protein variant to be cleaved and therefore activated by proteases other than its intended targets (MMP2, MMP9, and MMP14) and deliver 111In-LFE687A to tumor cells was not evaluated here." (PMID 30954944, 2019). "Induction of VM in primary tumours of 4T1+ASA/Cl mice was confirmed by higher expression of VE-cadherin (VE-CAD) and secretory leukocyte protease inhibitor (Slpi) with no change in MMP-9, all reported to be markers of VM." (PMID 29707148, 2018). "However, MMP-9 likely plays a role in the interaction of CSC and tumour niches, as opposed to MMP-2." (PMID 28606135, 2017). "However, the expression of MMP-1, MMP-2, and MMP-9 was not different between primary NSCLC tumor and metastatic lymph node (MMP-1 and MMP-9 not shown)." (PMID 28915603, 2017). "Similarly, oligo-HA, but not LMW- or HMW-HA, induced MMP-9, -13, and uPAR in Lewis lung carcinoma (LLC) tumor cells, thus facilitating matrix remodeling and tumor cell migration." (PMID 26029216, 2015). "However the differential expression of MMP2 by tumour cells does not appear to reflect the expected metastatic properties of these cells since metastatic MDA-MB-231 cells express little or no MMP2 and MMP9 in the extracellular medium." (PMID 26284589, 2015).
tumor (continued). "Similarly, MMP-9 expression was not an independent predictor for OS (p = 0.807); LVI and tumor stage were the only significant prognostic indicators for OS." (PMID 25888323, 2015). "Neutrophil-derived gelatinase B/MMP-9 also interacts with neutrophil NGAL, which prevent autolytic gelatinase B/MMP-9 processing but does not impair gelatinase B/MMP-9 activity, promoting tumour progression." (PMID 24473089, 2014). "However, since the autocrine CCL5 feedback loop fueled expression of MMP-9 by CSCs, it is possible that secreted MMP-9, a protease involved in ECM degradation, facilitates invasion also of neighboring non-CSC tumor cells." (PMID 24728412, 2014). "The reciprocal experiment where U937-derived supernatants were added to the tumor cells resulted in increased VEGF, but not MMP-9 secretion, and even this was not specific, as anti-EMMPRIN could not inhibit this effect." (PMID 23874303, 2013). "Therefore, macrophage infiltration and MMP-9 expression in the lung tissue were directly inhibited by IFN-α, irrespective of the presence of tumor." (PMID 23527047, 2013). "There were no changes of invasive behavior of embryos because of the inactivation of MMP-9, indicating that MMP-9 did not play a single and independent role in this phenomenon and mouse embryos could bypass the MMP-9 way to invade tumor cells." (PMID 22672566, 2012). "However, decrease in MMP-9 and VEGF at the tumour site did not impair angiogenesis, suggesting the presence of a bypass route e.g. up-regulation of fibroblast growth factor, although this remains to be established." (PMID 22005011, 2011). "In vivo evidence from the chicken chorionallantoic membrane assay showed that MMP-9 and u-PA are interdependent in tumor invasion, which also showed that invasion was dependent on both MMP-9 and u-PA, because in the absence of MMP-9 and u-PA, tumor cells showed only low levels of invasion." (PMID 19789215, 2011). "Moreover, another report also indicated that lipocalin 2 was possibly involved in invasion of tumor cells by regulating activity of MMP-9 and MMP-2, but was not apparently related with division and proliferation of tumor cells in SHEEC." (PMID 19077278, 2008). "Separate analyzes of MMP1, MMP2, MMP3, MMP9, TIMP1, TIMP2, and MTC1 in plasma do not allow a prognostic prediction for tumour grading, staging, or metastasis, but certain combinations could be very helpful." (PMID 16901349, 2006). "Extracellular MMP inducer expression was positively correlated with tumour size, depth of invasion, lymphatic invasion, expression of ki-67, MMP-2, MMP-9 and VEGF of tumours (P<0.05), but not with lymph node metastasis, UICC staging or differentiation (P>0.05)." (PMID 17088917, 2006). "The analysis of metalloproteinase expression levels in tumor (MDA) and non-tumor (MCF 10A) cell lines cultured in a 3D collagen matrix following treatment with MeOH and DCM extracts represent a novelty into the modulatory effects of these extracts on MMP-9 and MMP-2." (PMID 39409699, 2024). "Moreover, if the NGAL-mediated MMP-9-enhancing activity were preserved, disrupting the iron transport ability of NGAL would still guarantee the MMP-9 effects in inflammation, but would not affect its pro-metastatic role in tumor microenvironment." (PMID 34830212, 2021). "Even though the Cu (II)-DOTA-CTT inhibited MMP2 and MMP9 activities with binding affinities (EC50) of 8.7 μM and 18.2 μM, respectively, which are very similar to those of the original CTT (13.2 μM and 11.0 μM, respectively), it was not successful in in vivo tumor imaging." (PMID 33918106, 2021). "Investigators found that the tumours displayed reduced infiltration with CD45+ myeloid cells, diminished angiogenic activity, and persistent shrinkage with no regrowth, which may result from insufficient MMP-9 to induce neovascularization." (PMID 33803414, 2021).